RNU6-367P (RNA, U6 small nuclear 367, pseudogene)
Gene: Small nuclear RNA gene on chromosome 3 (44,071,087 to 44,071,186, forward strand). Ensembl gene ENSG00000252980.
Homologues: Orthologues: chimpanzee U6 (99% identical), macaque U6 (97% identical), guinea pig U6 (74% identical), dog U6 (70% identical), rat LOC120093912 (64% identical), pig U6 (60% identical). Paralogues in human: RNU6-1209P (77% identical), RNU6-46P (77% identical), RNU6-1311P (76% identical), RNU6-11P (75% identical), RNU6-1316P (75% identical), RNU6-188P (75% identical), RNU6-310P (75% identical), RNU6-37P (75% identical), RNU6-621P (75% identical), RNU6-778P (75% identical), RNU6-1145P (74% identical), RNU6-15P (74% identical), and 1283 more.